MRPL53 (mitochondrial ribosomal protein L53)
Synonyms: L53mt; mL53
Tractability: Small molecule: a structure with a bound ligand is known. PROTAC: ubiquitination databases record sites on it; its protein half-life has been measured.
Gene: Protein-coding gene on chromosome 2 (74,471,982 to 74,472,687, reverse strand). Ensembl gene ENSG00000204822.
Subcellular location: Mitochondrion
Subcellular location (Human Protein Atlas): Mitochondria
Pathways (Reactome):
Metabolism of proteins: Mitochondrial ribosome-associated quality control; Mitochondrial translation elongation; Mitochondrial translation initiation; Mitochondrial translation termination
Gene Ontology:
Molecular function: protein binding
Biological process: mitochondrial translation
Cellular component: mitochondrial large ribosomal subunit; mitochondrion; mitochondrial inner membrane
Genetic constraint (gnomAD): Loss-of-function variants: 7 observed, 8.79 expected, observed/expected ratio (o/e) 0.8, 90% interval 0.45 to 1.48. That is too few expected variants to judge how well the gene tolerates losing a copy. Missense variants: 185 observed, 172.54 expected, observed/expected ratio (o/e) 1.07, 90% interval 0.95 to 1.21. Synonymous variants: 84 observed, 71.07 expected, observed/expected ratio (o/e) 1.18, 90% interval 0.99 to 1.42.
Homologues: Orthologues: chimpanzee MRPL53 (99% identical), macaque MRPL53 (95% identical), mouse Mrpl53 (87% identical), guinea pig MRPL53 (84% identical).
Diseases named in the same sentence as MRPL53 in open-access papers:
MRPL53 is named in the same sentence as 6 diseases in open-access papers, as found by Europe PMC text mining. Sharing a sentence is not in itself a finding about the gene and the disease. The quoted sentences say what the papers report.
allergic rhinitis (1 paper, 2025). Inflammation of the nasal mucous membranes caused by an IgE-mediated response to external allergens. "As both CLPX and MRPL53 regulate fundamental cellular functions, they are likely to have some influence on the pathophysiology of allergic rhinitis." (PMID 39913623, 2025).
pan (1 paper, 2023). "In pan cancer, NXF2B, MSLNL, PCGF1, INO80B-WBP1, LBX2-AS1, MRPL53, LBX2, TTC31, WDR54 and WBP1 were co-altered in the TLX2-altered group." (PMID 37758722, 2023).
MRPL53 also shares sentences with these, for which no sentence is quoted: cancer (1 paper); lung adenocarcinoma (1); memory impairment (1); tumor (1).